SEMA3C (semaphorin 3C)
Description:
Binds to plexin family members and plays an important role in the regulation of developmental processes. Required for normal cardiovascular development during embryogenesis. Functions as attractant for growing axons, and thereby plays an important role in axon growth and axon guidance (By similarity).
Synonyms: SEMAE; SemE
Tractability: Antibody: UniProt places it where antibodies can reach, with medium confidence; UniProt predicts a signal peptide or a membrane-spanning region; its Gene Ontology location is reachable by antibodies, with medium confidence; the Human Protein Atlas places it where antibodies can reach.
Safety:
Unwanted effects reported when the protein is acted on. In parentheses: how it was acted on, where the effect was seen, and who reports it.
Neutropenia (source: ClinPGx)
Gene: Protein-coding gene on chromosome 7 (80,742,538 to 80,922,379, reverse strand). Ensembl gene ENSG00000075223.
Subcellular location: Secreted
Subcellular location (Human Protein Atlas): Cytosol; Golgi apparatus; Plasma membrane; Predicted to be secreted
Gene Ontology:
Molecular function: protein binding; chemorepellent activity; neuropilin binding; semaphorin receptor binding
Biological process: axon guidance; cardiac endothelial to mesenchymal transition; immune response; negative chemotaxis; neural crest cell migration; outflow tract septum morphogenesis; positive regulation of cardiac neural crest cell migration involved in outflow tract morphogenesis; positive regulation of cell migration; response to xenobiotic stimulus; semaphorin-plexin signaling pathway; cardiac right ventricle morphogenesis; limb bud formation; neural tube development; outflow tract morphogenesis; pulmonary myocardium development; somitogenesis
Cellular component: extracellular exosome; plasma membrane; extracellular region
Genetic constraint (gnomAD): Loss-of-function variants: 32 observed, 58.27 expected, observed/expected ratio (o/e) 0.55, 90% interval 0.41 to 0.74. The upper end of that interval is the gene's LOEUF score, 0.74, which puts it in group 3 of 6, group 1 being the genes least tolerant of losing a copy. Missense variants: 633 observed, 737.85 expected, observed/expected ratio (o/e) 0.86, 90% interval 0.8 to 0.92. Synonymous variants: 240 observed, 259.89 expected, observed/expected ratio (o/e) 0.92, 90% interval 0.83 to 1.03.
Homologues: Orthologues: chimpanzee SEMA3C (99% identical), macaque SEMA3C (99% identical), dog SEMA3C (97% identical), rabbit SEMA3C (97% identical), mouse Sema3c (97% identical), rat Sema3c (97% identical), pig SEMA3C (96% identical), guinea pig SEMA3C (95% identical), tropical clawed frog sema3c (83% identical), zebrafish sema3c (68% identical). Paralogues in human: SEMA3F (54% identical), SEMA3A (44% identical), SEMA3D (44% identical), SEMA3E (44% identical), SEMA3B (43% identical), SEMA3G (41% identical), SEMA4D (30% identical), SEMA5B (28% identical), SEMA4B (27% identical), SEMA4C (27% identical), SEMA4G (27% identical), SEMA5A (26% identical), and 7 more.
Diseases named in the same sentence as SEMA3C in open-access papers:
SEMA3C is named in the same sentence as 80 diseases in open-access papers, as found by Europe PMC text mining. Sharing a sentence is not in itself a finding about the gene and the disease. The quoted sentences say what the papers report.
prostate carcinoma (29 papers, 2014 to 2025). A carcinoma that arises from epithelial cells of the prostate gland. "Sema3C also seems to be involved in the progression of prostate cancer via the mutation of the transcription factor FOXA1 and even contributes to its resistance to therapy." (PMID 39457718, 2024). "In particular, we summarize SEMA3C’s role as an autocrine andromedin in prostate cancer growth and survival and provide an overview of other cancer types that SEMA3C has been implicated in including pancreas, brain, breast, and stomach." (PMID 30759745, 2019). "High SEMA3C expression is associated with unfavourable outcomes in glioma, breast, lung, liver, pancreatic, gastric, gynecological, and prostate cancers." (PMID 30759745, 2019). "Recent reports have implicated SEMA3C in angiogenesis and have also highlighted the significance and clinical relevance of SEMA3C in prostate cancer." (PMID 28038451, 2017). "High Sema3C expression increased motility and invasion of prostate cancer cells, whereas in ovarian cancer high levels of Sema3C were associated with shorter patient survival." (PMID 26032848, 2015). "Although these data may suffer from relevant discrepancy between gene expression at mRNA and protein levels, further analysis of Sema3C association with prostate cancer patients' prognosis and resistance to therapy is warranted." (PMID 33537086, 2021). "This could be explained by the fact that Sema3C may trans-activate multiple receptor tyrosine kinases involved in the growth of prostate carcinoma cells, and potentially also implicated in resistance to androgen-deprivation therapies." (PMID 33537086, 2021). "PlexinB1 and its ligands, Sema4D and Sema3C, are associated with tumor progression and bad prognosis of many tumor types, including breast, ovarian, glioma, and melanoma as well as prostate cancer." (PMID 31861264, 2019). "FOXA1's inhibitory effect on SEMA3C expression may also be of significance given that FOXA1, which is often found to be mutated in advanced PCa, may account for elevated SEMA3C expression in advanced prostate cancer." (PMID 28038451, 2017). "When assessing the potential biological importance of the analyzed variants, SEMA3C stood out, jointly due to its large number of NCCMs and the existing literature suggesting that overexpression of SEMA3C is linked to poor prognosis in several cancer types including prostate cancer and GBM." (PMID 32513296, 2020). "Our findings reveal that FOXA1 alterations lead to elevated levels of SEMA3C both in prostate cancer specimens and in vitro." (PMID 38528115, 2024). "Work presented here outlines one avenue of SEMA3C regulation and is intended to inspire future work which will be needed to fully understand the mechanisms governing elevated SEMA3C levels in prostate cancer patients containing FOXA1 alterations." (PMID 38528115, 2024). "Our results indicate that alterations to FOXA1 lead to increased SEMA3C expression levels in prostate cancer specimens and also in vitro." (PMID 38528115, 2024). "Here, we show that semaphorin 3C, a secreted signaling protein that is highly expressed in castration-resistant prostate cancer, can promote steroidogenesis by altering the expression profile of key steroidogenic enzymes." (PMID 37800655, 2023). "Consistent with this, in prostate cancer, the SEMA3C/PlexinA2/NRP1 axis has been shown to be correlated with PNI and nerve density within the tumor cancer model." (PMID 37719704, 2023). "They showed that Semaphorin 3C, a signaling molecule secreted by prostate cancer cells, can alter the expression of key steroidogenic enzymes, e.g., Cyp11a1." (PMID 38139309, 2023). "Overexpression of SEMA3C in prostate cancer cell lines facilitates stem cell marker CD44 expression and tumor-sphere formation, suggesting a role for SEMA3C in maintaining prostate CSCs." (PMID 35785187, 2022).
prostate carcinoma (continued). "Semaphorin-3C (SEMA3C) promotes prostate cancer growth by transactivating multiple receptor tyrosine kinases (RTK), including EGFR, via Plexin B1 receptor which has intrinsic GAP activity." (PMID 32674318, 2020). "SEMA3C is an indicator of poor prognosis in multiple cancer types and correlates with drug resistance in glioma, glioblastoma, and prostate cancer, possibly due to its high expression in cancer stem cells." (PMID 32241267, 2020). "For example, higher Sema3C levels in castration-resistant prostate cancer cells as well as in glioblastoma U87, bladder T24, and kidney Caki-2 cells activated phosphorylation of MET and EGFR, in a dose-dependent manner." (PMID 31726800, 2019). "It has been recently reported that SEMA3C drives the activation of multiple receptor tyrosine kinase pathways in prostate cancer cells, which is a key mechanism for mediating cancer growth, survival, and treatment resistance." (PMID 31649890, 2019). "Inhibition of either PlexinB1 or Sema3C significantly delays regrowth of prostate cancer xenografts in mice following castration or enzalutamide treatment." (PMID 31861264, 2019). "In clinical prostate cancer, high Sema3C expression levels are associated with resistance to ADT in patient derived xenografts and an increase in Sema3C is found in CRPC and bone metastases." (PMID 31861264, 2019). "We show here that activation of PlexinB1 by Sema4D and Sema3C results in translocation of endogenous GR to the nucleus in prostate cancer cells, and that this effect is dependent on PlexinB1 expression." (PMID 31861264, 2019). "PlexinB1, Sema4D, and Sema3C are overexpressed in prostate tumors and expression of Sema3C is an independent predictor of biochemical recurrence of prostate cancer." (PMID 31861264, 2019). "PlexinB1 and its ligand Sema3C have been shown to promote resistance to androgen receptor pathway inhibition in prostate cancer treatment." (PMID 31861264, 2019). "Expression of Sema3C in prostate cancer is induced by the androgen receptor and GATA2 and negatively regulated by FOXA1." (PMID 29642487, 2018). "Here, we show that SEMA3C is a secreted soluble autocrine growth factor that drives growth and treatment resistance of prostate cancer via activation of multiple RTKs such as EGFR, MET, and ErbB2 in a cognate ligand‐independent manner." (PMID 29348142, 2018). "Overexpression of Sema3C in prostate cancer cell lines enhances invasion and facilitates stem cell marker expression and tumorsphere formation, suggesting a role for Sema3C in maintaining prostate CSCs." (PMID 29642487, 2018). "As compared to prostate cancer cell lines, secreted SEMA3C expression was very low in immortalized benign prostate epithelial cell lines, RWPE‐1 and BPH‐1, respectively." (PMID 29348142, 2018). "Sema3C is an indicator of poor prognosis and progression of glioblastoma, prostate cancer, breast cancer, liver cancer, gastric cancer, pancreatic cancer, and lung cancer." (PMID 29642487, 2018). "SEMA3C inhibition represents a novel therapeutic strategy for treatment of advanced prostate cancer." (PMID 29348142, 2018). "We have recently shown that SEMA3C is an androgen receptor‐regulated gene that is induced by androgens in prostate cancer." (PMID 29348142, 2018). "In prostate cancer, increased expression of Sema3C strongly correlates with biochemical recurrence and castration resistance." (PMID 29642487, 2018). "In summary, this study identifies SEMA3C as a key secreted, autocrine growth factor that drives PCa growth and castration‐ and treatment‐resistant prostate cancer progression through activation of EGFR, HER2/ErbB2, MET, and c‐SRC tyrosine kinase pathways." (PMID 29348142, 2018). "Increased expression of Sema3C in prostate cancer tissues can also be attributed to hypomethylation of its promoter." (PMID 29642487, 2018).
prostate carcinoma (continued). "Given the role of Sema3C in androgen resistance, targeting Sema3C offers promise for patients with castration-resistant prostate cancer, who have few therapeutic options." (PMID 29642487, 2018). "Taken together, these data suggest that Plexin B1 and coreceptors, NRP1 and NRP2, mediate SEMA3C signaling in prostate cancer cells." (PMID 29348142, 2018). "SEMA3C is a secreted protein that can induce migratory and invasive properties of breast cancer and prostate cancer cells." (PMID 24586203, 2014). "Additionally, SEMA3C has been linked to the induction of EMT and stemness of prostate epithelial cells as well as increased prostate cancer invasion and migration." (PMID 38528115, 2024). "It should also be noted that while we have drawn a link between FOXA1, AR, and SEMA3C in prostate cancer, a direct causal relationship cannot be concluded without further studies." (PMID 38528115, 2024). "Nonetheless, our data demonstrate that alterations to FOXA1 have functional consequences and may be responsible for altered SEMA3C expression in prostate cancer specimens." (PMID 38528115, 2024). "Our findings underscore the key role of FOXA1 in prostate cancer progression and treatment resistance by regulating SEMA3C expression and suggest that SEMA3C may be a driver of growth and tumor vulnerability of mCRPC harboring FOXA1 alterations." (PMID 38528115, 2024). "Among all urological cancers, both sema3C and 4A have been studied in prostate cancer." (PMID 39457718, 2024). "But SEMA3C binds to NRP1 to promote prostate cancer cell perineural invasion by activating cMET." (PMID 37701532, 2023). "The ability of semaphorin 3C to promote intratumoral androgen synthesis was confirmed by the authors in castration-resistant prostate cancer patients by conferring continued growth of prostate tumors under androgen deprivation therapy associated with Semaphorin 3C upregulation." (PMID 38139309, 2023). "The authors reported up-regulation of Sema3C and downregulation of Sema3A and Sema3E levels after exposure to hypoxia or hypoxic mimetic agents, thus suggesting a different role of Sema3 family members in the progression of prostate cancer." (PMID 33858502, 2021). "Moreover, SEMA3C has been demonstrated to play a key role in maintaining stem-cell-like cell features in glioblastoma and prostate cancer." (PMID 32241267, 2020). "We hypothesize that in GBM tumors, both Sema3C overexpression and NaVP treatment operate via the same epithelial-to-mesenchymal transition mechanism as was shown in other studies with prostate cancer." (PMID 31726800, 2019). "In addition, overexpression of Sema3C increases the regrowth of prostate cancer xenografts following castration." (PMID 31861264, 2019). "In prostate cancer, Sema3C appears to modulate multiple mitogenic pathways." (PMID 29642487, 2018). "We have observed all forms of SEMA3C secreted from all of the prostate cancer cell lines." (PMID 29348142, 2018). "Considering the co-occurrence of aberrant AR and SEMA3C in advanced prostate cancer, we speculate that restored AR signaling in advanced PCa drives SEMA3C expression which in turn propels PCa progression." (PMID 28038451, 2017). "Given the implication of both AR and SEMA3C in prostate cancer development, in combination with the discovery of ARBSs within the SEMA3C locus, we hypothesized that SEMA3C is a transcriptional target of the androgen receptor." (PMID 28038451, 2017). "To address this gap, we identified semaphorin 3C (SEMA3C) as a candidate FOXA1 target gene that might mediate the pro-oncogenic effects such as increased proliferation and EMT linked with FOXA1 variants in prostate cancer." (PMID 38528115, 2024). "Interestingly, MAO-A promotes prostate cancer cell PNI through SEMA3C/PlexinA2/NRP1-cMET signaling." (PMID 36418844, 2023). "We next evaluated whether SEMA3C ASO could inhibit growth of ENZ‐resistant prostate cancer." (PMID 29348142, 2018).
prostate carcinoma (continued). "In prostate cancer cells, monoamine oxidase A (MAOA) enhances the levels of Semaphorin 3C (Sema3C), NRP-1, and Plexin-A2." (PMID 39769452, 2024). "Collectively, these findings suggest that SEMA3C may be a putative driver of the cancer-promoting activities associated with FOXA1 variants, implying that the FOXA1 alterations commonly observed in clinical prostate cancer samples might mediate their oncogenic effects via SEMA3C." (PMID 38528115, 2024). "The ability of semaphorin 3C to promote intratumoral androgen synthesis may be a key mechanism contributing to the reactivation of the androgen receptor pathway in castration-resistant prostate cancer, conferring continued growth under androgen deprivation therapy." (PMID 37800655, 2023). "To reinforce the idea that SEMA3C expression requires AR, we also showed that SEMA3C levels were not induced by R1881 in the AR-negative prostate cancer cells lines, PC-3 and DU 145, over the same concentrations." (PMID 28038451, 2017). "Thus, given SEMA3C’s ability to activate multiple RTK pathways and its key role in prostate cancer growth and survival, it is intriguing to speculate whether SEMA3C might also play an important role in driving angiogenesis, cell growth, cell survival and metastasis in other cancers." (PMID 30759745, 2019). "In prostate cancer cells, HRE sequences have been found in the promoter of Sema3A, Sema3B, Sema3C, Sema3E, and Sema3F genes, but not in Sema3D." (PMID 33858502, 2021). "Overexpression of Sema3C may confer resistance to Wnt inhibitors, not just in GBM, but also in other cancers such as breast and castration-resistant prostate cancers that also utilize both pathways." (PMID 37080989, 2023).